PSMD12 (proteasome 26S subunit, non-ATPase 12)
Description:
Component of the 26S proteasome, a multiprotein complex involved in the ATP-dependent degradation of ubiquitinated proteins. This complex plays a key role in the maintenance of protein homeostasis by removing misfolded or damaged proteins, which could impair cellular functions, and by removing proteins whose functions are no longer required. Therefore, the proteasome participates in numerous cellular processes, including cell cycle progression, apoptosis, or DNA damage repair.
Synonyms: p55; Rpn5; STISS
Tractability: Small molecule: an approved drug acts on it; a structure with a bound ligand is known; a high-quality ligand is known. Antibody: its Gene Ontology location is reachable by antibodies, with high confidence. PROTAC: UniProt records ubiquitination sites on it; ubiquitination databases record sites on it; its protein half-life has been measured.
Target class: Enzyme
Gene: Protein-coding gene on chromosome 17 (67,337,916 to 67,366,605, reverse strand). Ensembl gene ENSG00000197170.
Subcellular location (Human Protein Atlas): Microtubules; Cytosol; Nucleoplasm
Pathways (Reactome):
Immune System: AMPK-induced ERAD and lysosome mediated degradation of PD-L1(CD274); Activation of NF-kappaB in B cells; Antigen processing: Ubiquitination & Proteasome degradation; CLEC7A (Dectin-1) signaling; Cross-presentation of soluble exogenous antigens (endosomes); Dectin-1 mediated noncanonical NF-kB signaling; Downstream TCR signaling; ER-Phagosome pathway; FCERI mediated NF-kB activation; GSK3B-mediated proteasomal degradation of PD-L1(CD274); Interleukin-1 signaling; NIK-->noncanonical NF-kB signaling; Neutrophil degranulation; SPOP-mediated proteasomal degradation of PD-L1(CD274); TNFR2 non-canonical NF-kB pathway
Cell Cycle: APC/C:Cdc20 mediated degradation of Securin; APC/C:Cdh1 mediated degradation of Cdc20 and other APC/C:Cdh1 targeted proteins in late mitosis/early G1; Autodegradation of Cdh1 by Cdh1:APC/C; Autodegradation of the E3 ubiquitin ligase COP1; Cdc20:Phospho-APC/C mediated degradation of Cyclin A; FBXL7 down-regulates AURKA during mitotic entry and in early mitosis; G2/M Checkpoints; SCF(Skp2)-mediated degradation of p27/p21; SCF-beta-TrCP mediated degradation of Emi1; Separation of Sister Chromatids; The role of GTSE1 in G2/M progression after G2 checkpoint; Ubiquitin-Mediated Degradation of Phosphorylated Cdc25A; Ubiquitin-dependent degradation of Cyclin D
Signal Transduction: Asymmetric localization of PCP proteins; Degradation of AXIN; Degradation of DVL; Degradation of GLI1 by the proteasome; Degradation of GLI2 by the proteasome; Degradation of beta-catenin by the destruction complex; GLI3 is processed to GLI3R by the proteasome; Hedgehog 'on' state; Hedgehog ligand biogenesis; MAPK6/MAPK4 signaling; Negative regulation of NOTCH4 signaling; Regulation of PTEN stability and activity
and 28 more pathways
Gene Ontology:
Molecular function: protein binding
Biological process: cellular response to type I interferon; proteasomal protein catabolic process; proteasome-mediated ubiquitin-dependent protein catabolic process; regulation of proteasomal protein catabolic process; response to oxidative stress
Cellular component: extracellular exosome; membrane; proteasome complex; cytosol; extracellular region; ficolin-1-rich granule lumen; nucleoplasm; proteasome accessory complex; proteasome regulatory particle; proteasome regulatory particle, lid subcomplex; secretory granule lumen; synaptic vesicle
Genetic constraint (gnomAD): Loss-of-function variants: 6 observed, 51.08 expected, observed/expected ratio (o/e) 0.12, 90% interval 0.063 to 0.23. The upper end of that interval is the gene's LOEUF score, 0.23, which puts it in group 1 of 6, group 1 being the genes least tolerant of losing a copy. Missense variants: 376 observed, 495.01 expected, observed/expected ratio (o/e) 0.76, 90% interval 0.7 to 0.83. Synonymous variants: 153 observed, 172.42 expected, observed/expected ratio (o/e) 0.89, 90% interval 0.78 to 1.01.
Gene-disease validity (ClinGen):
ClinGen rates the evidence that PSMD12 causes each of these diseases.
Stankiewicz-Isidor syndrome (autosomal dominant): Definitive. A neurodevelopmental disorder characterized by delayed psychomotor development, intellectual disability, behavioral disorders, mild craniofacial anomalies, and variable congenital defects of the cardiac and/or urogenital systems.
Homologues: Orthologues: chimpanzee PSMD12 (100% identical), macaque PSMD12 (100% identical), dog PSMD12 (99% identical), pig PSMD12 (99% identical), guinea pig PSMD12 (99% identical), rat Psmd12 (98% identical), mouse Psmd12 (98% identical), rabbit PSMD12 (97% identical), tropical clawed frog psmd12 (91% identical), zebrafish psmd12 (87% identical), Drosophila melanogaster Rpn5 (52% identical), Caenorhabditis elegans rpn-5 (47% identical). Paralogues in human: COPS4 (19% identical).